CDK6 (cyclin dependent kinase 6)
Diseases named in the same sentence as CDK6 in open-access papers (continued):
Sharing a sentence is not in itself a finding about the gene and the disease.
esophagogastric adenocarcinoma (3 papers, 2021 to 2023). "Moreover, molecular dissection of the chromosome band 7q21 amplicon in gastroesophageal junction adenocarcinomas revealed upregulated CDK6 expression at both transcription and translation levels." (PMID 36788224, 2023).
liposarcoma (3 papers, 2023 to 2025). A usually painless malignant tumor that arises from adipose tissue. "In high-grade tumor proliferations like dedifferentiated liposarcoma, neoplastic growth is propelled by Rb 1 protein inactivation and mediated by cyclin D-dependent kinases, specifically CDK4 and CDK6." (PMID 40870476, 2025). "For instance, CDK4/CDK6 inhibitors (e.g., palbociclib) and MDM2 antagonists are under active investigation in clinical trials for advanced liposarcoma." (PMID 41488879, 2025).
mesothelioma (3 papers, 2019 to 2022). A usually malignant and aggressive neoplasm of the mesothelium which is often associated with exposure to asbestos. "Another tested drug in our screen, Palbociclib, PD0332991, a CDK4/CDK6 inhibitor, that is supposed to target the most frequent deletion in mesothelioma, CDKN2A, showed only minor effects in our cell lines." (PMID 34580349, 2021).
pulmonary arterial hypertension (3 papers, 2021 to 2024). Pulmonary arterial hypertension (PAH) is a group of diseases characterized by mean pulmonary artery pressure >20 mmHg and elevated pulmonary arterial resistance leading to right heart failure. "Downregulation of miR-637 increases the risk of pulmonary arterial hypertension by regulating the expression of CDK6 in pulmonary smooth muscle cells." (PMID 34606407, 2021). "Downregulation of hsa_circ_0002062 has the potential to block pulmonary vascular remodeling induced by CDK6, overexpression of which accelerates cell proliferation in pulmonary hypertension." (PMID 34322152, 2021).
renal cell carcinoma (3 papers, 2015 to 2021). "MiR-186, which uses CDK6 as a direct target, has been shown to decrease in vivo tumor development, cell proliferation, migration, and invasion in renal cell carcinoma." (PMID 34804161, 2021).
squamous cell lung carcinoma (3 papers, 2019 to 2025). A carcinoma arising from squamous bronchial epithelial cells.
uveal melanoma (3 papers, 2012 to 2021). A melanoma derived from melanocytes of the uveal tract. "We also provide evidence that c-Met was a target of miR-34b/c, and miR-34b/c decreased endogenous c-Met, phosphorylated v-akt murine thymoma viral oncogene homolog (p-Akt), cyclin-dependent kinase (CDK) 4, and CDK6 protein levels in uveal melanoma cells." (PMID 22419847, 2012). "MiR-137 acts as a tumor suppressor in uveal melanoma cell proliferation through downregulation of its targets MITF and CDK6; miR-34a acts as a tumor suppressor in uveal melanoma cell proliferation and migration through downregulation of c-Met." (PMID 23441115, 2013). "In addition, miR-137 has been found to suppress uveal melanoma cell growth by targeting MITF and CDK6." (PMID 22419847, 2012).
acute promyelocytic leukemia (2 papers, 2019 to 2020). An aggressive form of acute myeloid leukemia (AML), characterized by arrest of leukocyte differentiation at the promyelocyte stage, due to a specific chromosomal translocation t(15;17) in myeloid cells. "Another screen used DNA topoisomerase II (TOP2A) poison etoposide to identify TOP2A gene and cyclin-dependent kinase 6 (CDK6) in promyelocytic leukemia (PML) cell line HL60." (PMID 30636933, 2019). "By analyzing public databases, we observed that the messenger RNA (mRNA) levels of CDK6 were significantly overexpressed in AML cell lines and non-acute promyelocytic leukemia (non-APL) AML patients when compared to healthy donors." (PMID 33597968, 2020).
asthma (2 papers, 2023 to 2025). "Despite these limitations, our study identifies seven core targets (HSP90AB1, CCNB1, CCK, CDK6, CASP9, NR3C1, and ERBB2) that offer promising avenues for developing novel asthma therapies." (PMID 41403444, 2025).
autoimmune disease (2 papers, 2019 to 2025). A disorder resulting from loss of function or tissue destruction of an organ or multiple organs, arising from humoral or cellular immune responses of the individual to their own tissue constituents. "IL6ST is linked to RA, multiple sclerosis, autoimmune diseases, inflammatory bowel diseases, pneumonia, and Crohn’s disease, and is regulated by multiple drugs and phosphorylated by CDK6." (PMID 40839671, 2025).
bladder urothelial carcinoma (2 papers, 2021 to 2025). "Correspondingly, proteins related to cell cycle such as CDK4, CDK6 and Cyclin D1 were obviously diminished after specific siRNA treatment, which is consistent with the phenomenon that bladder urothelial carcinoma cells are largely arrested in the G1 phase." (PMID 33980246, 2021).
carcinoid (2 papers, 2015 to 2021). "In contrast, CCND1 (p = 0.0012) and CDK6 (p < 0.0001) showed elevated expression in carcinoids compared to carcinomas." (PMID 26008974, 2015). "In contrast, CCNE1 and CDK6 showed elevated expression in carcinoids compared to carcinomas." (PMID 26008974, 2015). "Four additional somatic mutations were detected in the DDR2 (p.Arg806Ter), CDK6 (p.Thr107Ser), and SMARCA4 gene (p.Arg1135Gln) were identified in the adenocarcinoma component, whereas no specific mutations were identified in the carcinoid component." (PMID 34926584, 2021).
Cerebral ischemia (2 papers, 2018 to 2021). Restriction of arterial blood supply to the brain associated with insufficient oxygenation to support the metabolic requirements of the tissue. "MiR-424 protects from permanent focal cerebral ischemia injury in mice through targeting CDK6 to inhibit microglia activation." (PMID 34215174, 2021). "We previously showed that exogenous overexpression of miR-424 in the brain protects against permanent focal cerebral ischemia injury via suppression of microglia-mediated inflammatory response by reducing the expression of cell cycle proteins CDK6, cyclin D1, CDC25A." (PMID 29675290, 2018).
cervical tumors (2 papers, 2019 to 2021). "ZNF382 was firstly identified as a direct repressor for several oncogenes (i.e., MYC, MITF, HMGA2, and CDK6) across distinct types of cancers, including lung, esophageal, colon, stomach, breast, and cervical tumors." (PMID 34638319, 2021). "In addition, aberrant expression of CDK6 were detected in cervical tumors." (PMID 30829464, 2019).
depression (2 papers, 2017 to 2019). "These protein targets, especially hubs, and the functional nodes, MTOR, CDK6, SHC1, RCOR1 CCNA2 and STAT3, have been already reported to be involved in depression." (PMID 28954415, 2017). "Personalized by gender and diagnosis, in female bipolar CDK6 was a strong predictor for state (AUC 100%, p = 0.007), in female PTSD SHMT1 was a strong predictor for trait first year ED visits (AUC 100%, p = 0.022), and in female depression GNG7 for trait all future ED visits (OR 14.54, p = 0.022)." (PMID 30755720, 2019).
esophageal adenocarcinoma (2 papers, 2020 to 2025). A malignant tumor with glandular differentiation arising predominantly from Barrett mucosa in the lower third of the esophagus. "Treatment with abemaciclib of rats bearing esophageal adenocarcinoma xenografts, established from three different cell lines, resulted in tumor volume reduction and down-regulation of cyclin D, CDK4, CDK6 and E2F1, compared with rats treated with placebo." (PMID 40699853, 2025). "Knockdown of CDK6 or CDK4 with small interfering RNA or pharmacologic inhibition with palbociclib led to proliferation suppression and inhibition of anchorage-independent survival in esophageal adenocarcinoma cells." (PMID 40699853, 2025).
Fanconi anemia (2 papers, 2017 to 2021). Fanconi anemia (FA) is a hereditary DNA repair disorder characterized by progressive pancytopenia with bone marrow failure, variable congenital malformations and predisposition to develop hematological or solid tumors. "Other involved pathways were again cell cycle signaling (15%, CDK6, CDK12), Fanconi anemia/DNA repair (15%, FANCD2, NBN), and additionally peroxisome proliferator-activated receptor (PPAR) signaling (8%, PPARG) as well as discoid in domain receptor 2 signaling (8%, DDR2)." (PMID 34200508, 2021).
gastric adenocarcinoma (2 papers, 2017 to 2022). "Of these, 8 regions contained previously characterized amplified oncogenes: GATA4, CCND1, CDK6, MDM2, EGFR, MCL1, ERBB3 and MYB; this is the first report of significant and nearly isolated MYB amplification in gastric adenocarcinoma." (PMID 28426752, 2017).
heart failure (2 papers, 2020 to 2024). Inability of the heart to pump blood at an adequate rate to meet tissue metabolic requirements. "The probability of heart failure was significantly increased in patients with high expression of SOCS3 and NRXN1, while the expression of CDK6 and SMAD4 was significantly reduced in patients without heart failure." (PMID 33224271, 2020).
hepatitis B (2 papers, 2016 to 2020). "Next, using the DIANA-mirPath program, we investigated the mechanism by which miR-214/199a/199a* activates hepatitis B signaling, pathways in cancer and cell cycle, and found that 3 central cell-cycle promoting genes, E2F2, CDK3 and CDK6 was strikingly enriched in these predicted targets pathway." (PMID 26498144, 2016).
Kaposi's sarcoma (2 papers, 2011 to 2022). A malignant neoplasm characterized by a vascular proliferation which usually contains blunt endothelial cells. "For example, the Kaposi sarcoma's Cyclin homolog (Uniprot accession Q98147) interacts with the human protein CDK6 (Cyclin-dependent kinase 6, Q00534), which is also known to interact with various human Cyclin proteins." (PMID 21760902, 2011). "For example, high levels of Cdk6 have been shown to induce apoptosis rather than proliferation in Kaposi's sarcoma." (PMID 35572197, 2022).
lymph node metastasis (2 papers, 2020 to 2021). "Consistently, we found that CDK6 was overexpressed in EJA tissues with lymph node metastasis and that a high CDK6 expression status is an independent predictor of poor prognosis in patients with EJA." (PMID 34152098, 2021). "In this study, we demonstrated that a high CDK6 expression status may promote lymph node metastasis and that a high LRP1B expression status inhibits lymph node metastasis in patients with EJA." (PMID 34152098, 2021). "A high CDK6 expression status may promote lymph node metastasis, while a high LRP1B expression status may inhibit lymph node metastasis." (PMID 34152098, 2021). "tNGS revealed that CDK6 and LRP1B mutation frequencies were significantly different between EJA cases with (N ≥ 1) or without (N = 0) lymph node metastasis." (PMID 34152098, 2021). "CDK6, MET, NOTCH1, and LRP1B mutation frequencies showed significant differences in cases with (N ≥ 1) or without (N = 0) lymph node metastasis." (PMID 34152098, 2021). "Together, our findings indicate that CDK6 and LRP1B have significant potential as indicators of prognosis and lymph node metastasis in patients with EJA and could be targeted for molecular targeted therapy." (PMID 34152098, 2021). "miR-206, CDK6, TNM stage and lymph node metastasis as independent prognostic factors." (PMID 33330087, 2020). "Specifically, the mutation frequencies of CDK6, MET, and NOTCH1 noticeably lower in cases with stage N0 than in those with stage N ≥ 1, whereas LRP1B mutation frequency was remarkably higher in cases without lymph node metastasis." (PMID 34152098, 2021).
lymphoid leukemia (2 papers, 2020 to 2025). A malignant lymphocytic neoplasm of B-cell or T-cell lineage involving primarily the bone marrow and the peripheral blood. "We here describe a novel option for combination and show that CDK6 balances metabolism and that its kinase inhibition leads to a switch to glycolysis in lymphoid leukemia." (PMID 39966356, 2025).
male infertility (2 papers, 2020 to 2022). The inability of the male to effect fertilization of an ovum after a specified period of unprotected intercourse. "A Cdk2 and Cdk6 dKO also results in infertility in both sexes, while a Cdk4 and Cdk6 dKO displays the same infertility seen in a Cdk4 single KO, with total female infertility and partial male infertility, signifying that Cdk6 does not have a dominant phenotype in mouse fertility." (PMID 32731332, 2020).
metastasis (2 papers, 2021). The spread or migration of cancer cells from one part of the body (where they first appeared) to another. "EphA2 protein expression was positively correlated with CDK6 protein expression, invasion depth, lymph node metastasis and clinicopathological stage (P < .05)." (PMID 33586348, 2021).
metastatic cancer (2 papers, 2015 to 2021). A carcinoma which has spread from the original site of growth to another anatomic site. "More recent therapeutic options include palbociclib, a selective inhibitor of the cyclin-dependent kinases CDK4 and CDK6, approved for women with advanced metastatic cancer." (PMID 34783649, 2021). "Genes in the CMCG group (CDK4, CDK6, CDK8, GSK3B) had the most frequent copy number alterations in 86% of the primary and 65% of the metastatic cancers." (PMID 26420498, 2015).
myeloproliferative disorder (2 papers, 2021 to 2023). A clonal hematopoietic stem cell disorder, characterized by proliferation in the bone marrow of one or more of the myeloid (i.e., granulocytic, erythroid, megakaryocytic, and mast cell) lineages. "CDK6 ablation has a major effect on the myeloproliferative disorder, but also on inflammation inhibiting NFκB and TGF-β signaling." (PMID 37771602, 2023). "Additionally, CDK6 facilitates the development of myeloproliferative neoplasm by increasing cytokine production and activating LSC." (PMID 33599085, 2021).
myeloproliferative neoplasm (2 papers, 2020 to 2021). "A prominent example is JAK2V617F-driven myeloproliferative neoplasm (MPN), where CDK4/6 kinase inhibition does not mimic the anticancer effects induced by deletion of CDK6." (PMID 33255177, 2020).
osteoporosis (2 papers, 2021 to 2024). A condition of reduced bone mass, with decreased cortical thickness and a decrease in the number and size of the trabeculae of cancellous bone (but normal chemical composition), resulting in increased fracture incidence. "It is interesting to note that miR‐34s serve as an inhibitor in osteoblast proliferation by decreasing levels of Cyclin D1, CDk4, and CDK6 and a suppressor in osteoblast differentiation by decreasing SATB2 to facilitate the progression of osteoporosis." (PMID 33434305, 2021). "This osteoporosis may be attributed to the intracellular accumulation of iron, which induces G1 cell cycle arrest in osteoblasts, accompanied by downregulation of Cyclin D1, Cyclin D3, CDK2, CDK6, and CDK6 expression, thereby suppressing osteoblast proliferation." (PMID 39022306, 2024).
Parkinson disease (2 papers, 2022 to 2024). A progressive degenerative disorder of the central nervous system characterized by loss of dopamine producing neurons in the substantia nigra and the presence of Lewy bodies in the substantia nigra and locus coeruleus. "FBXO7 gene regulates ubiquitin-dependent CyclinD/CDK6 degradation and maintains mesenchymal gene expression and mutations have been associated with Parkinson's disease but it's role in the liver has not been determined." (PMID 38291075, 2024).
pheochromocytoma (2 papers, 2015 to 2020). "Somatic mutations in exon 3 of the p18INK4c-encoding gene disrupting p18INK4c interaction with CDK4 or CDK6 were also detected in MTC and pheochromocytoma patients." (PMID 25900242, 2015). "It was pointed out that upregulation of CDK6 and activation of the PI3K/AKT pathway alleviated hypoxia-induced pheochromocytoma cell injury." (PMID 33224271, 2020).
Primary microcephaly (2 papers, 2022 to 2025). Head circumference below 2 standard deviations below the mean for age and gender at birth. "A homozygous CDK6 missense mutation (p.Ala197Thr) was previously reported in a family with primary microcephaly." (PMID 40210435, 2025).
psoriasis (2 papers, 2008 to 2020). An autoimmune condition characterized by red, well-delineated plaques with silvery scales that are usually on the extensor surfaces and scalp. "STAT3, p-STAT3, UBE2N and CDK6 are downregulated by the overexpression of hsa-miR-4516, which is consistently upregulated in psoriasis and induces apoptosis in HaCaT cells." (PMID 32785106, 2020).
retinoblastoma (2 papers, 2015 to 2019). A malignant tumor that originates in the nuclear layer of the retina. "A series of canonical pathways, including those involved in Rb (Retinoblastoma)/E2F cell cycle (Rb, E2f2, E2f3, E2f5, Cdk6, DHFR), Notch (Dll1, Notch 2, Jag1), Wnt (Wnt, Axin2, Wisp2/Ccn5) and NF-κB (Ikbip) were found to participate in this network." (PMID 30742662, 2019). "We found that the expression of Cyclin E and CDK2 was downregulated in retinoblastoma cells with TAZ knockdown, but no obvious changes were observed in Cyclin D1, CDK4 and CDK6 expression." (PMID 26464030, 2015).
seminoma (2 papers, 2020 to 2022). A radiosensitive malignant germ cell tumor found in the testis (especially undescended), and extragonadal sites (anterior mediastinum and pineal gland). "Interestingly, CDK6 was amplified in 2.6% of seminomas, while CCND3 (CyclinD3; 1.7%) and CHEK1 (6.8%) were amplified or deleted in non-seminomas, respectively." (PMID 32418994, 2020). "Our data revealed that YAP1/CDK6/CDK4/cyclinD1/RB could be a potential therapeutic axis in TGCTs and sequential regimens of metformin and cisplatin could be a useful therapy for human seminomas and non-seminomas." (PMID 35264157, 2022).
skin carcinoma (2 papers, 2019 to 2021). "Indeed, qPCR assays show that WNT signalling enhanced CyclinD transcription in both Cdkn2a KO and Cdkn2ab KO MEFs and transcription of both Cdk6 and CyclinD in the skin carcinoma cell lines." (PMID 30926782, 2019).
thymic atrophy (2 papers, 2015 to 2021). "CDK6 has a central role in hematopoiesis and CDK6-deficient mice show reduced production of erythrocytes, granulocytes, macrophages, neutrophils, and thrombocytes, as well as thymic atrophy." (PMID 34065376, 2021). "CDK6 is predominantly expressed in hematopoietic cell types and loss of CDK6 in mice causes thymic atrophy and reduction in red blood cells, granulocytes, macrophages, neutrophils and platelets, as well as delayed G1 progression in lymphocytes of Cdk6−/− mice." (PMID 25914884, 2015).
thymic lymphoma (2 papers, 2014 to 2023). "In addition, CDK6 deficiency protected mice from AKT-driven thymic lymphoma." (PMID 37893220, 2023). "This was followed in each independent clone of the thymic lymphoma by the amplification or overexpression of cyclin Ds and Cdk6." (PMID 25452272, 2014).
adenovirus infection (1 paper, 2021). "The results clearly showed that the expression of CDK6, not CDK4, inhibited by matrine was significantly rescued by the c-Myc adenovirus infection, not by the Control adenovirus infection, in SU-DHL-16 cells, which identified that CDK6 is a bona fide c-Myc target gene in SU-DHL-16 cells." (PMID 34088288, 2021).